ITPKA (inositol-trisphosphate 3-kinase A)
Diseases named in the same sentence as ITPKA in open-access papers (continued):
Sharing a sentence is not in itself a finding about the gene and the disease.
tumor (13 papers, 2013 to 2026). "In addition to neurons, many tumor types express ITPKA, due to promoter demethylation, mutation of the transcription repressor REST, or gene body methylation." (PMID 36688944, 2023). "Since the regulation of actin dynamics essentially controls metastasis of tumor cells, we first intended to analyze the impact of the actin bundling activity for ITPKA-controlled migration, which is one essential step in the metastatic cascade." (PMID 36688944, 2023). "ITPKA contributes to tumor proliferation, migration and cell death in-vitro, moreover, we provide evidence that TFAP2A transcriptionally induce the hyper-expression of ITPKA." (PMID 32015686, 2020). "GSEA was introduced for potential mechanism exploring 8-10, and the transcriptome data from 50 TCGA_LUAD tumor tissues were submitted for GSEA (based on ITPKA expression, top 25 (top 10%) versus bottom 25 (bottom 10%) from 511 TCGA_LUAD tumor samples)." (PMID 32015686, 2020). "Up-regulation of ITPKA in tumor cell lines with low endogenous ITPKA expression increases migration." (PMID 30352093, 2018). "The average level of ITPKA expression in tumor tissues was significantly higher than that in non-tumor tissues (1.11 versus 3.01, P < 0.001, paired Student’s t test)." (PMID 26249031, 2015). "The median fold change of ITPKA (1.84) in HCC tumor tissues was used as a cutoff value to divide all 135 patients into two groups: the high expression group (n = 66) and the low expression group (n = 69)." (PMID 26249031, 2015). "Our prior RNA-seq profiling data showed that ITPKA was overexpressed in all ten tested HCC tumor tissues." (PMID 26249031, 2015). "High expression of ITPKA has been reported to promote migration of tumor cells by two different mechanisms: ITPKA increases calcium entry that directly influences cell migration in EGF stimulated cells." (PMID 24564989, 2013). "Based on the functional activities of increasing invasive migration of tumor cells, ITPKA might become an innovative target for inhibiting invasion and metastasis of primary tumors." (PMID 36685893, 2022). "ITPKA promotes cell motility and the metastatic potential of tumor cells." (PMID 24058270, 2013). "ITPKA is a cell motility-promoting protein that increases the metastatic potential of tumor cells." (PMID 24564989, 2013). "Moreover, the ITPKA expression is significantly higher in lymph node positive and more aggressive T stage LUAD tissues, indicating that ITPKA might contribute to the tumor progression and metastasis." (PMID 32015686, 2020). "Tumor tissues exhibited substantial upregulation of TFF1, UBE2C, ITPKA, and IGFBP3, alongside concurrent downregulation of SELENBP1 and SLC34A2, relative to matched normal samples." (PMID 40787454, 2025). "Comparing tumor cells (B-CPAP cell line) and normal cells (Nthy-ori 3-1 cell line), the expression levels of model genes (PAPSS2, ITPKA and CYP1A1) were as expected." (PMID 36685893, 2022). "Consistent with the in vitro study, overexpression of ITPKA impaired the tumorigenicity of OVCAR3 cells, as demonstrated by the tumor weight values." (PMID 33879633, 2021). "To identify the differential expression of ITPKA in LUAD, we first analyzed the TCGA_LUAD dataset which containing 511 tumor samples and 58 normal samples (57 pairs) with clinical parameters." (PMID 32015686, 2020). "Univariate analysis showed that HBsAg, serum AFP level, tumor size, tumor number, vascular invasion, TNM stage, and ITPKA expression were prognostic factors for OS and RFS." (PMID 26249031, 2015). "The qRT-PCR results revealed pronounced upregulation of TFF1, ITPKA, UBE2C, and IGFBP3, along with marked downregulation of SLC34A2 and SELENBP1 in tumor samples relative to adjacent normal tissues, which was in strong agreement with the transcriptomic profiling outcomes." (PMID 40787454, 2025).
tumor (continued). "Among the 57 paired tissues (LUAD tumor tissues vs. their adjacent normal tissues), there are 2 normal tissues with null ITPKA expression but not their adjacent LUAD tissues." (PMID 32015686, 2020). "Overexpression of inositol-1,4,5-trisphosphate-3-kinase-A (ITPKA) was observed in all ten HCC tumor tissues compared with their matched nontumoral counterparts." (PMID 26249031, 2015). "Further studies showed that ITPKA, one member of our 6-MRG risk signature, could not be found in the public-available proteomic data (Clinical Proteomic Tumor Analysis Consortium)." (PMID 37460577, 2023).
immune disease (1 paper, 2023). "Although there was substantial evidence of ITPKA on carcinogenesis and metastasis, the role and regulation of ITPKA in inflammatory or immune disease remains less unknown." (PMID 36857861, 2023).
respiratory system diseases (1 paper, 2025). "Previous studies showed an association between GIPR and C-reactive protein levels and ITPKA was found to be related to respiratory system diseases, while PIK3C2B was reported to be associated with lung function." (PMID 40251596, 2025).
ITPKA also shares sentences with these, for which no sentence is quoted: Anxiety (2 papers); adenocarcinoma (1); allergic disease (1); anxiety disorder (1); Cognitive impairment (1); gastric cancer (1); glioblastoma (1); Huntington disease (1); invasive breast carcinoma (1); lung squamous cell carcinoma (1); renal diseases (1); thyroid carcinoma (1); α-synucleinopathy (1).